KLK5 (kallikrein related peptidase 5)
Diseases named in the same sentence as KLK5 in open-access papers (continued):
Sharing a sentence is not in itself a finding about the gene and the disease.
tumor (continued). "In multivariable analysis, KLK5 mRNA expression lost significance (p = 0.095), which may be either due to the relative low numbers of included cases or its association with the strong clinical factor ‘residual tumor mass’, which remains as an independent factor (p < 0.001)." (PMID 31307411, 2019). "In previous OC-related studies it has been described that KLK5 expression is correlated with progressive disease as well as higher tumor grade." (PMID 31307411, 2019). "In 41 of the 138 cases, KLK5 antigen levels - determined in cytosolic tumor tissue extracts by ELISA - were available." (PMID 31307411, 2019). "A significantly increased proportion of tumors displaying elevated KLK5 mRNA expression (p = 0.041) was observed in the patient group with post-operative residual tumor (44%, 29/66), compared to the tumor-free group (27%, 19/70)." (PMID 31307411, 2019). "We assessed the mRNA expression levels of KLK5 in tumor tissue of 138 patients using quantitative PCR (qPCR)." (PMID 31307411, 2019). "The base model included the clinical parameters age, residual tumor mass, and ascites fluid volume to which the parameter KLK5 mRNA expression was subsequently added." (PMID 31307411, 2019). "For example, high KLK5 and KLK6 tumor tissue levels are associated with an advanced disease stage and significantly shorter progression-free survival (PFS) and overall survival (OS) times." (PMID 25436002, 2015). "Nonetheless, other molecular mechanisms by which KLK5 influences tumour behaviour are yet to be elucidated." (PMID 25593998, 2014). "This was in agreement with diminished or completely inactivated expression of KLK5 in a panel of normal breast cell strains and tumor cell lines." (PMID 24158494, 2014). "Kallikrein-related peptidase 5 (KLK5) is overexpressed in normal versus cancerous prostatic tissue, and an inverse relationship has been reported between KLK5 levels and pathologic tumor stage and grade." (PMID 24809052, 2014). "An intriguing novel finding of our present analysis is the inverse correlation of KLK5 and ezrin, a membrane cytoskeleton linker protein, which has been shown to increase tumor motility and invasion, and is considered key to the metastatic process." (PMID 25593998, 2014). "We found a strong positive relation between KLK5 expression and tumour grade (P = 0.006) and disease stage (P = 0.027)." (PMID 11237385, 2001). "In multivariate analysis, KLK5 expression showed independent prognostic value only in the subset of tumours with lower grade disease (grades I and II)." (PMID 11237385, 2001). "KLK5 may inhibit EMT through different mechanisms during tumor progression in metaplastic TNBC, which needs further exploration." (PMID 38090381, 2023). "KLK5 mRNA was upregulated in GBC tumor specimens when compared with paired peritumoral tissues." (PMID 36313631, 2022). "Moreover, as a COX-2 associated gene in TNBC, we found KLK5 and KLK7 gene KOs to restore tumor cell sensitivity to celecoxib both in vitro and in vivo." (PMID 33588911, 2021). "Our investigation of possible associations between KLK5 mRNA expression and clinical pathological parameters demonstrated that in advanced HGSOC there is a significant association between elevated KLK5 mRNA expression and residual tumor mass after surgery." (PMID 31307411, 2019). "Together with previous findings of clinical, biochemical, and cell biological studies pointing to a tumor-supporting role of KLK5, this kallikrein-related peptidase may be regarded as a novel target for therapy of OC and presumably of other cancers as well." (PMID 31307411, 2019). "In fact, there is only one study pointing to a tumor-suppressive function of KLK5 in tumor tissue." (PMID 31307411, 2019).
tumor (continued). "A multivariate logistic regression analysis was adjusted to Log10KLK5 expression levels, the tumor size and the age of the patients with the intention to examine the independence of the differential diagnosis potential of the KLK5 mRNA expression between the malignant and benign breast specimens." (PMID 21906360, 2011). "Interestingly, an increased expression of KLK5 in tumor-associated stromal cells, but not in tumor cells, was found to be related to a favorable clinical outcome." (PMID 31307411, 2019). "Thus, KLK5 overexpression might contribute to unfavorable prognosis in OC patients via supporting tumor cell shedding from the primary tumor as well as cleavage of extracellular matrix proteins during metastasis." (PMID 31307411, 2019). "For the first time and quite initriguingly our findings link KLK5, an extracellular protease, to cancer cell metabolism and indicate that inhibition of the mevalonate pathway may represent a novel mode of tumor suppression by proteases and a potential pharmacological target for anticancer therapy." (PMID 24158494, 2014). "Notably, clone C8 that produces sub-physiological concentration of KLK5 was suppressed to a lesser extend in terms of tumor onset and final sizes by approximately 6-fold smaller indicating that the tumor-suppressing effects of KLK5 are dependent on its concentration." (PMID 24158494, 2014). "One substrate of KLK5 is PAR2, which triggers pro-inflammatory mediators and induces the expression of NF-κB target genes in both immune cells and tumor cells." (PMID 36835153, 2023). "A growing body of evidence suggests tumor-supporting roles of several members of the kallikrein-related peptidase (KLK) family, including KLK5 and KLK7, in this cancer subtype." (PMID 33087135, 2020). "For instance, kallikrein genes KLK5, KLK6 and KLK7 were downregulated in HPV16+ tumours and co-expressed with two overlapping antisense transcripts: CTB-147C22.8 and CTB147C22-9, as well as KLK10 with its antisense CTC-518B2.12." (PMID 29263803, 2016). "While the levels of FASN mRNA remained unaltered, KLK5-expressing cells exhibited significantly lower rates of free fatty acid (FFA) biosynthesis, which may be linked to suppressed malignancy since it is well-established that decreased FFA is associated with reduced aggressiveness of tumor cells." (PMID 24158494, 2014). "These KLK4–7 expressing OV-MZ-6 cells increased tumor growth in an animal model compared to OV-MZ-6 cells expressing the single KLK4, KLK5, KLK6 or KLK7, or vector controls." (PMID 24043563, 2014). "Conversely, genes implicated in tumor progression, including Arghef18 and NfκB1, were downregulated in HPV transgenic mice lacking Klk5 and Klk7." (PMID 40753921, 2025). "Comparing the bulk transcriptome profiles of the TD and nonTD patients, the TD patients exhibited upregulation of keratins (KRT81, KRT6B, KRT15, KRT5) and kallikreins (KLK5, KLK6, KLK7), indicating active extracellular matrix (ECM) remodeling and tumor expansion." (PMID 39664386, 2024). "This analysis led to the identification of the genes CX3CL1, CCL28, PROM1, and KLK5, which were highly expressed in the boundary cells and not in tumor cells, myoepithelial cells or any other colocalized cell type." (PMID 38114474, 2023). "The expression of KLK5 was measured in GBC cells and tumor samples." (PMID 36313631, 2022). "Furthermore, we found MFGE8, KLK5, and KLK7 knockout (KO) to restore celecoxib sensitivity in TNBC cells leading to marked reductions in primary tumor growth." (PMID 33588911, 2021). "Briefly, scrambled, MFGE8, KLK5, and KLK7 KO cells generated in the MDA-MB-231 background were transplanted into the mammary fat pad of NSG mice (1 × 106 cells per mouse) and allowed for orthotopic tumor growth." (PMID 33588911, 2021).
tumor (continued). "Previously determined KLK5 mRNA as well as KLK5 and KLK7 antigen concentrations were used to evaluate the relationship between the expression patterns of both factors on the mRNA as well as protein level in tumor tissue of HGSOC patients." (PMID 33087135, 2020). "Interestingly, larger KLK5 level differentials (between primary tumor and omentum metastasis), as measured by ELISA, were also associated with shorter PFS, which may indicate a tumor-supporting role of KLK5 also during metastasis and not only in primary tumor growth." (PMID 31307411, 2019). "Through meta-analysis of published datasets, we identified tumor expression of PRSS3 and KLK5 transcripts as prognostic of poor survival and cancer progression in LAC but not SCC, which indicates that the pathways studied may be specific to LAC." (PMID 30755669, 2019). "Kallikrein-related peptidase 5 (KLK5) is overexpressed in normal tissues compared to cancerous prostatic ones and it shows an inverse relationship between KLK5 levels and pathologic tumor stage." (PMID 26007739, 2015). "Furthermore, the prognostic impact of established clinical factors and the analyzed KLK5–7 and KLK13 concentrations in tumor tissue was also analyzed in this independent collective." (PMID 25436002, 2015). "We speculate that the M and MSL subtypes may be driven by EMT‐related pathways, so KLK5 expression affects tumor prognosis, while the IM subtype is mainly driven by IM mechanisms, so KLK5 does not have an influence." (PMID 38090381, 2023). "In addition, we hypothesize that the potential synergistic effects of COX-2 inhibition and some genes KO (KLK5/7, MFGE8) on suppressing TNBC primary tumor growth might be due to convergent inhibition of different aspects of tumorigenesis." (PMID 33588911, 2021). "Indeed, KLK5 has recently been shown to cleave ECM (collagens type I, II, III, IV, fibronectin, and laminin) and adhesion molecules (fibrinogen and vitronectin), suggesting a role in tumor invasion and angiogenesis." (PMID 33588911, 2021). "The aim of the current study was the expression analysis of KLK5 in cancerous and benign breast lesions, targeting the evaluation of the clinical use of KLK5 expression for the discrimination of the malignant from the non-cancerous tumors of the mammary gland." (PMID 21906360, 2011).
cancer (26 papers, 2004 to 2025). A tumor composed of atypical neoplastic, often pleomorphic cells that invade other tissues. "High KLK5 levels in serum were detected by enzyme‐linked immunosorbent analysis in some patients with ovarian (69%) and breast (49%) cancer." (PMID 38090381, 2023). "It is of note that in other cancer cell types functional analyses have demonstrated an association of KLK5 with invasiveness and cell-cell cohesion." (PMID 31307411, 2019). "The mechanisms underlying the cancer suppressing effects of KLK5 merit further investigation." (PMID 24158494, 2014). "KLK5 is a kallikrein-related peptidase and is recognized as a prognostic biomarker for cancer; more research was urgently needed to discover the role of KLK5 in CSF from NPSLE patients." (PMID 37684700, 2023). "KLK5 is an oncogenic protein involved in inflammation, tumorigenesis, radiotherapy resistance and drug resistance in several cancers." (PMID 36313631, 2022). "Having found that KLK5 knockdown phenocopied the effects of PRSS3 knockdown on cancer cell invasion and proliferation, we next evaluated the potential association of KLK5 gene expression in LAC with survival and progression." (PMID 30755669, 2019). "KLK5 has also been demonstrated to interact with α2-integrins, resulting in suppression of invasion of cancer through ectodomain regulation." (PMID 25593998, 2014). "Furthermore, we show that inhibition of EMTs may underlie the cancer suppressing effects of KLK5." (PMID 24158494, 2014). "The human kallikrein 1-related peptidases KLK4 and KLK5 are also potent activators of pro-HGFA in the cancer cell microenvironment." (PMID 25268161, 2014). "AP2α was indeed found to interact with the predicted sites on the GAS2 and on KLK-5 upstream regulatory sequences in the cancer cells as well as to the AP2α binding site in the promoter of the estrogene receptor gene used as a positive control (ESR1)." (PMID 21876733, 2011). "The median (50th percentile) value of the KLK5 expression (41.5 c/Kc) in the cancer patients' specimens was found to be approximately 105-fold decreased, compared to that found in the non-cancer patients' breast tissues (median: 4374.1 c/Kc)." (PMID 21906360, 2011). "Similar to the cytokine profiling results, most of the cancer‐associated proteins, such as ANGPTL4, KLK5, GAL3, VIM, HERs, CAPG, HO, CTSD, and AFP were produced at higher levels on the aged matrix, but were reduced to young matrix levels after LOX siRNA treatment." (PMID 34617419, 2021). "Together, these observations are consistent with the hypothesis that mesotrypsin promotion of cancer cell invasion and proliferation might be mediated through KLK5." (PMID 30755669, 2019). "Kallikrein-related peptidase 5 (KLK5) displays aberrant expression in cancer." (PMID 24158494, 2014). "We confirmed these results both experimentally by reconstituting KLK5 expression in cell lines, and clinically by showing a correlation between KLK5 expression and a number of these miRNAs in high metastatic potential cancers such as luminal B and Her-2 enriched subtypes." (PMID 25593998, 2014). "The potential utility of KLK5 as a cancer biomarker has been reported." (PMID 25593998, 2014). "However, the correlation of the KLK5 expression with the ER-negative status of the cancer patients is in contrast with the up-regulation of KLK5 expression by estrogens." (PMID 21906360, 2011). "The KLK5 expression analysis in the collected breast tissues revealed a statistically significant (p < 0.001) down-regulation of the gene transcription levels in the malignant tumor specimens compared to the benign ones." (PMID 21906360, 2011). "KLK5, 6, 10 and 12 were all downregulated in cancer compared to normal." (PMID 14710225, 2004). "Therefore, overexpression of HAI-1 might play an important role in the inhibition of pro-HGF-activating proteases and KLK5, which induced inhibition of cancer cell growth." (PMID 40299447, 2025).
cancer (continued). "Moreover, in several cancer types KLK5 and KLK7 co-expression has been observed." (PMID 33087135, 2020). "However, the implications of KLK5 levels vary in different cancers." (PMID 31572680, 2019). "Therefore, KLK5 has been considered to be the regulator of KLKs extracellular proteolytic cascade, counterbalancing the molecular microenviroment between normal physiology and cancer." (PMID 21906360, 2011). "Our current results showed impaired matriptase-mediated migration in KLK5 KO OSCC cells, supporting a potential role of this pathway in cancer invasion and metastasis." (PMID 34503205, 2021). "The potential of KLK5 and KLK7 as therapeutic targets in cancer has led to advances in the development of the first generation of KLK-based inhibitors." (PMID 33588911, 2021). "KLK5 and L1CAM play important roles in cancer progression (including cell proliferation, migration, angiogenesis, invasion, and metastasis), and their expression levels are associated with prognosis." (PMID 31572680, 2019). "The mRNA expression status of the KLK5, KLK6, KLK7, KLK8 and KLK9 has been extensively studied in cancer." (PMID 29229980, 2017). "In cancer tissues, pro-HGFA is likely activated by thrombin and/or human kallikrein 1-related peptidase (KLK)-4 and KLK-5." (PMID 25268161, 2014). "Targeting KLK5, KLK7, and KLK14 may pave the way for novel treatments that prevent cancer progression." (PMID 40753921, 2025). "Further analysis suggested that modulation of angiogenesis-related genes (including ANGPTL4, FN1, HSPG2, SRPX2, KLK5, L1CAM, Prr22, FOXJ1, IL24, and TRIM54) potentially contributes to anlotinib resistance, as anlotinib is a multi-targeted anti-angiogenesis drug for cancer therapy." (PMID 31572680, 2019).
infection (2 papers, 2018 to 2022). The state of being infected such as from the introduction of a foreign agent such as serum, vaccine, antigenic substance or organism. "We observed a significant upregulation of HAT and Furin, especially KLK5, after infection, whereas TMPRSS2 and Matriptase were barely stimulated." (PMID 34826211, 2022).
benign tumors (1 paper, 2011). "Considering this significant and central role of KLK5, we used a quantitative real-time RT-PCR (RT-qPCR) assay for the KLK5 expression quantification in 102 malignant and benign tumor breast tissues." (PMID 21906360, 2011). "The quantification of KLK5 expression in breast tissue biopsies may be considered as a novel and independent biomarker for the differential diagnosis between malignant and benign tumors of the mammary gland." (PMID 21906360, 2011).
head and neck tumors (1 paper, 2021). "Although in this study we focused on protein-coding genes, we noted top two highly up regulated non-coding transcripts in KLK6 high group samples, i.e., CTB-147C22.8 and CTB147C22, which were reported to be co-expressed with kallikrein genes KLK5, KLK6, and KLK7 in HPV16+ head and neck tumors." (PMID 34065672, 2021).
neurological disease (1 paper, 2016). "Thirdly, we present 19 protein control concentration values, four of which (sortilin, CCL16, cystatin B, KLK5) have not, to our knowledge, previously been reported for adult individuals without neurological disease." (PMID 26914813, 2016).
KLK5 also shares sentences with these, for which no sentence is quoted: ichthyosis (3 papers); skin disorder (3); esophageal cancer (2); lung carcinoma (2); telangiectasis (2); triple-negative breast carcinoma (2); anaplastic breast carcinoma (1); bladder carcinoma (1); bladder tumors (1); brain cancer (1); clear cell renal cell carcinoma (1); colon adenocarcinoma (1); colorectal adenocarcinoma (1); cutaneous squamous cell carcinoma (1); eczema (1); esophageal adenocarcinoma (1); gallbladder carcinoma (1); gastric cancer (1); glioblastoma (1); glioma (1); hyperlipidemia (1); Hypertension (1); lymph node metastasis (1); Obesity (1); osteogenesis imperfecta (1); Palmoplantar keratoderma (1); pancreatic adenocarcinoma (1); pancreatic cancer (1); pancreatic tumor (1); papillary renal cell carcinoma (1).
A further 7 diseases each share a sentence with KLK5 in 1 paper.